SERPINB3 (serpin family B member 3)
Diseases named in the same sentence as SERPINB3 in open-access papers (continued):
Sharing a sentence is not in itself a finding about the gene and the disease.
endometrial cancer (1 paper, 2023). Primary or metastatic malignant neoplasm involving the endometrium (mucous membrane that lines the endometrial cavity). "SerpinB3 and transmembrane protease serine 11D (TM11D) were almost threefold higher in endometrial cancer respectively." (PMID 36807337, 2023).
Fanconi anemia (1 paper, 2022). Fanconi anemia (FA) is a hereditary DNA repair disorder characterized by progressive pancytopenia with bone marrow failure, variable congenital malformations and predisposition to develop hematological or solid tumors. "In detail, decreasing SERPINB3 expression reduces the USP1‐mediated deubiquitination of FANCD2–FANCI in the Fanconi anemia pathway, thereby interfering with cisplatin‐induced DNA interstrand crosslinks repair and further contributing to HNSCC cell apoptosis." (PMID 36382555, 2022). "A pH‐responsive RNAi nanoplatform for targeted regulation of SERPINB3 function and effective inhibition of the Fanconi anemia (FA) pathway to promote cancer therapy." (PMID 36382555, 2022).
ischemia (1 paper, 2021). A hypoperfusion of the BLOOD through an organ or tissue caused by a PATHOLOGIC CONSTRICTION or obstruction of its BLOOD VESSELS, or an absence of BLOOD CIRCULATION. "The tissue-protective properties of EVs expressing SerpinB3 could be exploited for the protection and recovery from acute and chronic ischemic damage, as in patients with myocardial infarction or with critical ischemia of the lower limbs." (PMID 34451800, 2021).
liver steatosis (1 paper, 2023). "Mitoquinone and ASA significantly reduced liver steatosis and inflammation by decreasing the expression of TNFα, IL-6, Serpinb3, and cyclooxygenase 1 and 2 and restoring the anti-inflammatory IL-10." (PMID 37107346, 2023).
metabolic syndrome (1 paper, 2024). A cluster of metabolic risk factors for CARDIOVASCULAR DISEASES and TYPE 2 DIABETES MELLITUS. "In this study, C/EBP-β has been indeed reported as one of SerpinB3 transcription factors and plays a role in metabolic syndrome." (PMID 39061218, 2024). "This review explores the multifaceted roles of SerpinB3, focusing on its implications in fibrosis, metabolic syndrome, carcinogenesis and immune system impairment." (PMID 39061218, 2024).
papilloma (1 paper, 2021). A benign epithelial neoplasm that projects above the surrounding epithelial surface and consists of villous or arborescent outgrowths of fibrovascular stroma. "Serpinb3a/b3b/b3c and -b3d are orthologs of human SERPINB3 and B4, and we confirmed their differential expression in Mcpip1eKO papillomas." (PMID 34903245, 2021).
polyp (1 paper, 2024). A usually exophytic mass attached to the underlying tissue by a broad base or a thin stalk. "Thirdly, both recurrent (5 of 24) and primary polyp samples were used to evaluate the expression of SerpinB3 and B4 in this study." (PMID 38550710, 2024).
prurigo nodularis (1 paper, 2025). Prurigonodularis (PN) is a skin disease in which hard crusty lumps are formed on the skin that itches intensely. "However, the expression of SERPINB3/4 in the serum of patients with moderate‐to‐severe prurigo nodularis (PN) remains poorly understood." (PMID 40995892, 2025).
Pruritus (1 paper, 2025). Pruritus is an itch or a sensation that makes a person want to scratch. "Future studies should explore the relationship between SERPINB3/4 and other clinical parameters, such as itch mediators (e.g., IL‐31, TSLP) and neuronal activation markers, to better understand its role in pruritus." (PMID 40995892, 2025). "In patients with PN, the expression of serum SERPINB3/4 was significantly elevated in subjects with higher investigator global assessment (IGA) scores, while exhibiting a notable decline in patients with higher pruritus numeric rating scale (P‐NRS) scores." (PMID 40995892, 2025).
pulmonary emphysema (1 paper, 2025). A subcategory of chronic obstructive pulmonary disease (COPD). "Recent data have shown that SERPINB3 has a protective role in mediating tissue repair, especially during hypoxic conditions, through its proliferative action, suggesting a role in the development of pulmonary emphysema through the decreased repair capability in lung tissue of these patients." (PMID 40243422, 2025).
rhinitis (1 paper, 2022). An inflammation of the mucous membrane lining the nose, usually associated with nasal discharge. "Both APOH and SERPINB3 are upregulated in AR, suggesting that APOH may be involved in an upregulated state in rhinitis, while SERPINB3 acts at different stages of pathogenesis." (PMID 35628512, 2022).
skin inflammation (1 paper, 2024). "SERPINB4 and SERPINB3 were also significantly upregulated [log2 (fold change) of 4.09 and 3.21], respectively) and are known to be correlated with AD severity and are increasingly recognized as a biomarker in skin inflammation." (PMID 38344408, 2024).
soft tissue sarcoma (1 paper, 2019). A malignant neoplasm arising from muscle tissue, adipose tissue, blood vessels, fibrous tissue, or other supportive tissues excluding the bones. "In approximately 10% of soft-tissue sarcomas, largely irrespective of histological subtype and possibly independent of JUN amplification status, JNK inhibitors that can replace the inhibitory function no longer provided by SERPINB3 may restore JNK activity to normal condition." (PMID 31562358, 2019).
steatosis (1 paper, 2024). Increased lipid within the cytoplasm of cells. "•SerpinB3 is a mediator of liver inflammation, steatosis and fibrosis." (PMID 38307387, 2024). "The small molecule 1-PPA is effective in the control of steatosis, inflammation and fibrosis in NASH experimental models through the inhibition of PAR2 activation and of its downstream molecules, like C/EBP-β and SerpinB3, implicated in metabolic alterations and NASH." (PMID 38307387, 2024). "In particular, as recently reported, SerpinB3 was able to influence the hepatic levels of Galectin 3, CD9 and TREM2, typical markers of NAMs, a population of hepatic macrophages emerging in progressive NAFLD-NASH and strictly associated with severity of steatosis, inflammation as well as fibrosis." (PMID 38307387, 2024).
type II diabetes (1 paper, 2024). "Considering a putative role in relation to NAFLD/NASH patients, which are mostly obese individuals and/or type II diabetes patients, by inducing HIF-2α stabilization SerpinB3 may represent a factor able to deeply affect lipid metabolism." (PMID 38307387, 2024).
tumor (210 papers, 1995 to 2026). "While our integrative analyses identify robust associations between epithelial SERPINB3 expression, stromal immune mimicry, and immune-suppressive tumor microenvironments, functional experiments will be required to establish causality." (PMID 41595458, 2025). "In vivo, xenograft tumor experiments also demonstrated that re‐expression of SERPINB3 partially restored the reduced xenograft tumor growth caused by knockdown of TMEM65." (PMID 40546127, 2025). "SERPINB3 (SCCA1) has been implicated in promoting tumor progression, EMT, and immune evasion in hepatocellular carcinoma, cervical cancer, and lung cancer." (PMID 41595458, 2025). "Elevated levels of SERPINB3 in P66shc-downregulated tumors inhibit Caspase-8 activity, rendering tumor cells more susceptible to necroptosis." (PMID 38918587, 2024). "The positive relation between SerpinB3 and beta-catenin, associated with more aggressive tumours, was also reported in colorectal cancer." (PMID 37509293, 2023). "Cancerous squamous cell‐associated genes such KRT5, CDKN2A, and SERPINB3 were mainly enriched in the Stereo‐seq tumor areas, IGKC and IGLC2 were enriched in inflammatory areas, VIM in stromal areas, ADRA2A in blood vessels, and MUC5B in glands." (PMID 35986392, 2022). "In particular, we observed an association between higher SerpinB3 expression and larger tumor size, supporting the oncogenic function of SerpinB3 in tumor progression." (PMID 30717317, 2019). "Briefly, SCCA is a tumor product encoded by the SERPINB3 and SERPINB4 genes, whose tissue expression and serum concentrations increase in patients with HNSCC." (PMID 31151143, 2019). "To investigate further the role of serpinB3 in tumor progression, we analyzed the association between SerpinB3 expression and tumor size." (PMID 30717317, 2019). "In HPV-negative HNSCC, a strong association was found between SERPINB3/B4 mRNA levels and the presence of a denser tumor immune infiltrate, an IFN-Gamma signature and the expression of the immune checkpoint regulator PD-L1." (PMID 31151143, 2019). "High expression of SERPINB3 was indeed significantly associated with early tumor recurrence, which is commonly regarded as a true metastasis, due to dissemination of primary tumor cells then representing a subset of most aggressive HCCs." (PMID 25594056, 2014). "Therefore, the cancer cells mainly expressed the known CSCC‐associated gene SERPINB3 (serpin family B member 3), tumor genes TP63, CDKN2A, and keratin gene KRT5 in squamous cells." (PMID 35986392, 2022). "In conclusion, our findings identified a new molecular pattern in patients affected by HCC where elevated levels of SerpinB3 associated with p66shc downregulation showed markedly better survival, likely because tumor cells were more prone to die by necroptosis." (PMID 33922660, 2021). "Indeed, in HCC patients high levels of SerpinB3 were significantly associated with early tumour recurrence and poor prognosis." (PMID 28611447, 2017). "Furthermore, high levels of SERPINB3 expression have been significantly associated with early tumor recurrence." (PMID 27167107, 2016). "Along these lines, in a recent human study some of us reported that high levels of SERPINB3 transcripts were detectable in 15 out of 67 human HCC specimens (approx. 22%) and that high expression levels of SERPINB3 were significantly associated with early tumor recurrence." (PMID 25544768, 2015). "SERPINB3 is believed to contribute to tumour progression by protecting cancer cells from immune surveillance, thereby facilitating therapeutic evasion." (PMID 41362277, 2026). "SERPINB3 enhances the survival ability of tumor cells by regulating cytokine activity and signaling pathways related to tumor development." (PMID 40297811, 2025). "Immunohistochemistry images from the HPA database also manifested that the protein expression levels of ANLN, LY6D, and SERPINB3 are notably higher in PC tumor tissues." (PMID 41427028, 2025).
tumor (continued). "Previous studies have identified SERPINB3/4 as tumor markers for certain squamous cell carcinomas, with potential utility as prognostic biomarkers in various cancers." (PMID 40995892, 2025). "STRING network analysis further positioned SERPINB3 as a mechanistic hub linking tumor-intrinsic signaling to stromal remodeling and immune evasion." (PMID 41595458, 2025). "In different types of cancer its overexpression correlates with tumor aggressiveness; however, in acute oxidative stress conditions, SerpinB3 promotes cell survival." (PMID 39061218, 2024). "Reduced tumor sensitivity to chemotherapy and an impairment in the immune surveillance induced by high SerpinB3 expression was also demonstrated in esophageal carcinoma with a poor prognosis." (PMID 39061218, 2024). "Despite the similarity in CCA classification and tumor size between the two groups, patients with high SerpinB3/4 scores (2+/3+) were more frequently classified as TNM stage III/IV (64.3% vs. 31.3%, p = 0.031)." (PMID 38201652, 2024). "The increased immunosuppressive myeloid cell populations provide a possible mechanism for the high metastatic tendency of SERPINB3 tumors and represent a potential target for tumor control." (PMID 37279067, 2023). "Of note, we also found that SERPINB3 gene can be used as a tumor regulator through qRT-PCR validation, which can provide diagnosis and prognosis prediction for future biomarkers in BC patients." (PMID 37965307, 2023). "More important, targeting SERPINB3 in combination with RT showed significant tumor growth inhibition and improved RT-induced T cell immunity." (PMID 37279067, 2023). "We illustrate a possible classification of HCC based on the tumour immune infiltration and give evidence about the role of SerpinB3, a serine protease inhibitor involved in the regulation of the immune response in different cancers." (PMID 37509293, 2023). "Here, we provide the rationale for targeting an upstream, tumor-specific signal — SERPINB3 — as a more effective approach in the clinical setting." (PMID 37279067, 2023). "To further investigate the mechanistic and functional role of SERPINB3 in tumor progression, we utilized an orthotopic PDAC mouse model." (PMID 37980563, 2023). "Activation of the Wnt family members in relation to SerpinB3 expression was also assessed in the tumor tissue of 38 patients with HCC." (PMID 37372056, 2023). "Despite being a clinical biomarker, the modulation of SERPINB3 in tumor immunity is poorly understood." (PMID 37279067, 2023). "Of note, a study investigating its role in cervical cancer found that high expression of SerpinB3 was related to immune-exhausted TME and a higher risk of tumour progression and recurrence." (PMID 37509293, 2023). "Targeting CD11b+ myeloid cells or SERPINB3 both reduced tumor growth, however, the latter in combination with RT demonstrated more sustained inhibition of tumor growth and remodeling of infiltrating myeloid cells." (PMID 37279067, 2023). "To overcome this limitation, we re-assessed these RCD routines in human immortalized tumor cell lines that expressed high levels of SERPINB3 (human mSerpinb3a orthologue)." (PMID 35022507, 2022). "Taken together, this body of evidence contributes to the understanding of regulated cell death occurring in tumor cells in response to therapeutic ionizing radiation, and identified a targetable vulnerability, SERPINB3." (PMID 35022555, 2022). "A nude tumor‐bearing mouse model was established by the injection of a CAL‐27 SERPINB3 knockdown cell line (shSERPINB3) constructed by shRNA transfection into the right back." (PMID 36382555, 2022). "We performed immunohistochemical staining to evaluate the expression of NF-κB, HIF-2α, and SerpinB3 in the tissues of tumor-bearing mice." (PMID 36285158, 2022). "p66shc−/− mice and xenograft models were also used to assess the effects of p66shc and SerpinB3 on tumor growth." (PMID 33922660, 2021).
tumor (continued). "Mechanisms of tumor growth induced by SERPINB3 include the inhibition of intra-tumor infiltration by natural killer cells, up-regulation of Myc oncogene, and participation in Ras-mediated signaling." (PMID 33562077, 2021). "SerpinB3 has been found to be overexpressed in several types of tumor, especially in those with poor prognosis, including breast, liver, esophagus and colorectal cancer, although some findings have suggested its ability to inhibit cancer cell invasion." (PMID 33922660, 2021). "The aim of the study was to evaluate the expression of the pro-apoptotic p66shc and the anti-apoptotic SerpinB3 in HCCs in relation to clinical outcome, cell fate and tumor growth." (PMID 33922660, 2021). "Scid mice inoculated with HepG2/SerpinB3 cells showed significantly lower tumor growth, with weight and volume of tumor masses at sacrifice 5 and 6 times lower, respectively, than those detected in mice injected with HepG2/control cells." (PMID 33922660, 2021). "Subcutaneous tumor xenografts were generated in immunodeficient mice to verify the effect of the pattern characterized by low p66shc and high SerpinB3 in tumor growth." (PMID 33922660, 2021). "Taken together, these data demonstrate that miR-122 regulates SerpinB3 and that SerpinB3 contributes, at least in part, to the modulation of stem cell phenotype exerted by the tumor suppressor miR-122 in HCC." (PMID 30717317, 2019). "In particular, the emerging evidence related to the biological activity of SerpinB3 in tumor microenvironment is of relevance since it outlines two putative novel therapeutic targets involved in cell proliferation and HCC development and progression." (PMID 31817100, 2019). "Recently, we reported the expression profile of the best-characterized miRNAs in liver cancer cells and we identified some tumor-suppressive miRNAs, including miR-122, which are modulated by the ov-serpin SerpinB3." (PMID 30717317, 2019). "It has been identified that oncogenic RAS protein upregulates SERPINB3/4 and subsequent cytokine production and tumor growth." (PMID 30038719, 2018). "Recently, the protease inhibitor SerpinB3 has been described overexpressed in more advanced stages of this tumor." (PMID 28178650, 2017). "In sections of non-tumor mucosa SerpinB3 was barely detected and a faint positivity of COX-2 and β-Catenin was observed mainly in the cytoplasm." (PMID 28178650, 2017). "It is worth to note that in sequential tumor sections the highest signal of SerpinB3 was detected in areas showing high positivity for COX-2 and β-Catenin, indicating a possible relationship among these molecules." (PMID 28178650, 2017). "SerpinB3 has been recently described as an early marker of liver carcinogenesis, but the potential mechanistic role of this serpin in tumor development is still poorly understood." (PMID 26634820, 2015). "It has been reported that both serpinB3 and serpinB4 protect neoplastic cells from apoptosis and that serpinB3 promotes tumour growth, epithelial to mesenchymal transition and cell proliferation." (PMID 22808225, 2012). "SERPINB4 and SERPINB3 are serine protease inhibitor to modulate the host immune response against tumor cells." (PMID 20377895, 2010). "Previous studies have not clearly indicated SERPINB3 expression in tumor-associated macrophages or microglia, and its function within these cells remains entirely unexplored." (PMID 41550507, 2026). "Together, these pathways recapitulate the stromal and immune features validated in the imaging dataset, indicating that SERPINB3 may function as a molecular bridge connecting tumor-intrinsic programs with stromal reprogramming and immune suppression." (PMID 41595458, 2025). "S100A9, which we found up-regulated in pT1-HG biopsies, was identified as a protein associated with iNOS activity, and it is also involved in the regulation of signal transduction, such as SOD2, APOA1, HSP90, HSPA5, HINT1, MYDGF, and SerpinB3, and in immunomodulation in tumor microenvironments." (PMID 41441336, 2025).